PRMT7 (protein arginine methyltransferase 7)
Diseases named in the same sentence as PRMT7 in open-access papers (continued):
Sharing a sentence is not in itself a finding about the gene and the disease.
schizophrenia (2 papers, 2019 to 2021). A major psychotic disorder characterized by abnormalities in the perception or expression of reality. "PRMT7 was significantly associated with schizophrenia in our PrediXcan analyses and one of the most associated SNPs in our GWAS is just upstream of the gene." (PMID 31579629, 2019). "Increased predicted expression of PRMT7 associated with schizophrenia in 32 of 33 tissues in GTEx tested." (PMID 31579629, 2019). "Effect sizes were also positive for PRMT7 associations with schizophrenia in 42 of 42 tissues tested in our S-PrediXcan application to the PGC data (Schizophrenia Working Group of the Psychiatric Genomics Consortium, 2014)." (PMID 31579629, 2019). "In our PrediXcan analyses, we identified PRMT7 (P = 5.5 × 10−6, local false sign rate = 0.12) as significantly associated with schizophrenia following an adaptive shrinkage multiple testing adjustment." (PMID 31579629, 2019). "Schizophrenia was associated with increased expression of PRMT7 in 32 of 33 tissues in which it was predicted in the GAIN cohort." (PMID 31579629, 2019). "When S-PrediXcan was applied to the PGC summary stats, increased expression of PRMT7 was associated with schizophrenia in all 42 tissues in which expression was predicted." (PMID 31579629, 2019). "In addition to the PRMT7 association with schizophrenia, we identified rs10168049 (P = 1.0 × 10−6) as a potential candidate locus for bipolar disorder with highly divergent allele frequencies across populations, highlighting the need for diversity in genetic studies." (PMID 31579629, 2019). "Genome-wide association studies and PrediXcan (a gene-based association method) for schizophrenia and bipolar disorder identified that PRMT7 was significantly correlated with schizophrenia." (PMID 34712331, 2021). "While not found to be significantly associated with schizophrenia in brain tissues, the association of PRMT7 in adrenal gland and other vascular system organs highlights the sharing of eQTLs across tissues." (PMID 31579629, 2019).
acrodysostosis (1 paper, 2023). Acrodysostosis (ACRDYS) is a rare primary bone dysplasia characterized by severe brachydactyly, peripheral dysostosis with facial dysostosis, nasal hypoplasia, and developmental delay. "However, unlike PRMT7-related disorder, these are all autosomal dominant disorders caused by heterozygous variants in GNAS (PHP 1A and 1C), PRKAR1A and PDE4D (acrodysostosis), and/or 2q37 deletion resulting in loss of the HDAC4." (PMID 36399134, 2023).
acute lymphoblastic leukemia (1 paper, 2025). Leukemia with an acute onset, characterized by the presence of lymphoblasts in the bone marrow and the peripheral blood. "It has been found that PRMT7 regulates the expression of RUNX1 target genes in T cell acute lymphoblastic leukemia (T-ALL) and plays an active role in the pathogenesis of T-ALL." (PMID 41154773, 2025).
AIDS (1 paper, 2020). A syndrome resulting from the acquired deficiency of cellular immunity caused by the human immunodeficiency virus (HIV). "In addition, further study is needed into how the expression levels of PRMT5 and PRMT7 contribute to the progression of a patient from HIV-1 infection to development of AIDS." (PMID 32210193, 2020).
Anxiety (1 paper, 2020). Intense feelings of nervousness, tension, or panic often arise in response to interpersonal stresses. "The PRMT7 KO mice showed normal anxiety-like behaviors in the elevated plus-maze and the light/dark test." (PMID 32269286, 2020). "Collectively, these results suggest that PRMT7 deficiency specifically impairs social interaction in mice without altering the general anxiety levels or spontaneous seizures." (PMID 32269286, 2020).
chronic myeloid leukemia (1 paper, 2025). "Additionally, genetic loss of PRMT7 induced reprogramming of glycine metabolism that eradicated leukemic stem cells in mouse and human models of chronic myeloid leukemia (CML)." (PMID 40869229, 2025).
citrullinemia (1 paper, 2022). Citrullinemia is an autosomal recessively inherited disorder of urea cycle metabolism and ammonia detoxification characterized by elevated concentrations of serum citrulline and ammonia. "A previous study showed that PRMT7 interacts with ASS1, and that several mutations associated with citrullinemia disrupt this interaction." (PMID 35309121, 2022).
cognitive deficits (1 paper, 2021). "Notably, patients with PRMT7 mutations displayed neuron-deficient phenotypes, such as cognitive deficits, brain abnormalities, and seizures, suggesting PRMT7 may play crucial roles in neural development." (PMID 34712331, 2021).
herpes simplex infection (1 paper, 2021). "The PRMT7 methylome is enriched in proteins associated with the spliceosome, RNA transport, mRNA surveillance pathway, and herpes simplex infection." (PMID 33782401, 2021). "Furthermore, the results of the Kyoto Encyclopedia of Genes and Genomes (KEGG) pathway analysis revealed that PRMT7 methylome is implicated in spliceosome, mRNA surveillance pathway, RNA transport, and herpes simplex infection." (PMID 33782401, 2021). "KEGG pathway analysis results revealed that the top four most enriched pathways for PRMT4 and PRMT5 methylomes were spliceosome, mRNA surveillance pathway, RNA transport, and herpes simplex infection, which were similar to those for PRMT7 methylome." (PMID 33782401, 2021).
invasive breast carcinoma (1 paper, 2015). A carcinoma that infiltrates the breast parenchyma. "Therefore, we assessed the expression of MMP9 in invasive breast cancer cells depleted of PRMT7." (PMID 25605249, 2015).
ischemic cardiomyopathy (1 paper, 2025). Ischemic cardiomyopathy is a cardiomyopathy in which a weakness in the muscle of the heart due to inadequate oxygen delivery to the myocardium with coronary artery disease being the most common cause. "Our findings establish PRMT7 as a promising therapeutic target for modulating ER stress and promoting angiogenesis in ischemic cardiomyopathy." (PMID 40764455, 2025).
leishmaniasis (1 paper, 2020). Infectious disease that is transmitted through the bite of hematophagous female phlebotomine sand flies. "We previously linked PRMT7 levels to L. major parasite virulence and leishmaniasis pathogenesis." (PMID 32365184, 2020). "Despite not being an essential protein in L. major, PRMT7 levels regulate leishmaniasis disease pathology." (PMID 32365184, 2020).
lung fibrosis (1 paper, 2022). "In mouse models of COPD, lung fibrosis and skin injury, reduced expression of PRMT7 associates with decreased recruitment of monocytes to the site of injury and hence less severe symptoms." (PMID 35288557, 2022).
metastatic disease (1 paper, 2015). "This evidence suggests that PRMT7 expression may increase in early tumour development and then remain elevated in metastatic disease." (PMID 25605249, 2015). "Furthermore, elevated PRMT7 expression is maintained within the tumours potentially contributing to progression to metastatic disease." (PMID 25605249, 2015).
myocardial infarction (1 paper, 2025). Gross necrosis of the myocardium, as a result of interruption of the blood supply to the area, as in coronary thrombosis. "This study focuses on a protein called PRMT7, which may help heart cells recover after a heart attack." (PMID 40764455, 2025). "The study concludes that targeting endothelial PRMT7 could be a promising strategy for treating heart attacks." (PMID 40764455, 2025).
Osteopenia (1 paper, 2025). Osteopenia is a term to define bone density that is not normal but also not as low as osteoporosis. "Importantly, osteopenia caused by PRMT7 deletion in female mice can be rescued by PTEN overexpression, emphasizing the importance of PTEN in the PRMT7-mediated regulation of bone regeneration." (PMID 40243588, 2025). "This identifies PRMT7 as a key regulator of PTEN, opening new avenues for developing therapeutic strategies aimed at enhancing bone regeneration and treating bone-related disorders, such as osteopenia and osteoporosis." (PMID 40243588, 2025).
renal carcinoma (1 paper, 2024). A carcinoma arising from the epithelium of the renal parenchyma or the renal pelvis. "PRMT7 regulates the expression of the proto-oncogene c-MYC and has been shown to promote renal cancer cell growth and accelerate tumor development in a c-MYC dependent manner." (PMID 38911125, 2024).
seminoma (1 paper, 2008). A radiosensitive malignant germ cell tumor found in the testis (especially undescended), and extragonadal sites (anterior mediastinum and pineal gland). "We found that another type II protein arginine methyltransferase, PRMT7 is expressed in TCAM2 seminoma cells and that PRMT7 interacts with BLIMP1 as well." (PMID 18992153, 2008). "So we speculate that in IGCNU and seminoma, BLIMP1 recruits PRMT7 to compensate for the lack of nuclear PRMT5 to mediate H2A and H4 dimethylation." (PMID 18992153, 2008).
Smith-Magenis syndrome (1 paper, 2021). Smith-Magenis syndrome (SMS) is a complex genetic disorder characterized by variable intellectual deficit, sleep disturbance, craniofacial and skeletal anomalies, psychiatric disorders, and speech and motor delay. "These include a region located within the MHC, another located on chromosome 17 containing DLG2, TOM1L2, and overlapping the Smith-Magenis syndrome deletion, and another on chromosome 16 containing CENPT and PRMT7." (PMID 33646943, 2021).
Splenomegaly (1 paper, 2021). Abnormal increased size of the spleen. "These PRMT7-CKO mice exhibited significant splenomegaly, and their splenic cells showed decreased mature marginal zone B cells and increased follicular B cells, which indicated that PRMT7 deficiency impaired late B cell differentiation and promoted germinal center hyperplasia." (PMID 34712331, 2021).
thyroid cancer (1 paper, 2025). "Studies have shown that the /IGF2BPs/PRMT7 axis, in which PRKCQ-AS1 is involved, is an ideal therapeutic target for the diagnosis and treatment of thyroid cancer." (PMID 40597380, 2025).
cancer (20 papers, 2015 to 2025). A tumor composed of atypical neoplastic, often pleomorphic cells that invade other tissues. "Conclusively, a HCC-susceptible SNP rs73613962 at an intronic enhancer region of PRMT7 is identified, and its causal role in cancer-related phenotypes is demonstrated." (PMID 35264579, 2022). "It has been reported that PRMT7 is closely associated with embryonic stem cells, induced pluripotent stem cells, muscle stem cells, and human cancer stem cells." (PMID 34712331, 2021). "PRMT7-driven substrate methylation further leads to the biological outcomes of gene expression regulation, cell stemness, stress response, and cancer-associated phenotypes such as cell migration." (PMID 34440512, 2021). "PRMT7 is a key factor in the diagnosis of cell proliferation and distant metastasis in breast 23, liver 24, and lung 25 cancers, and the unlimited proliferation and distant metastasis of cancer cells are important causes of recurrence and death in patients." (PMID 37781082, 2023). "There is also evidence supporting a role for PRMT7 in an additional hallmark of cancer." (PMID 25605249, 2015). "Aberrant PRMT7 expression has been reported in human malignancies and plays vital roles in the progression of cancer." (PMID 37781082, 2023). "As global epigenetic changes through modification of methylation patterns play key roles in cancer development and progression, PRMT7’s role is evident and clear in PTC." (PMID 38092752, 2023). "In cancer tissues of GSE25097, the expressions of PRMT2, PRMT3, PRMT4, PRMT5, and PRMT7 were upregulated in cancer tissues, whereas the expressions of PRMT6 and PRMT9 were downregulated." (PMID 37627211, 2023). "In GSE36376, the expressions of PRMT1, PRMT2, PRMT3, PRMT4, PRMT5, and PRMT7 were upregulated in cancer tissues." (PMID 37627211, 2023). "The roles of these DEmiRNAs are involved in cell proliferation, cancer growth and metastasis, and adipogenesis, which are similar to the functions of Prmt7." (PMID 36013373, 2022). "Abrogation of PRMT7 not only inhibited the proliferation of various human cancer cells but also suppressed DSB repair pathways, both HR and NHEJ, leading to cellular senescence." (PMID 36293180, 2022). "Among the top 20 significantly enriched pathways, we identified pathways in cancer, signaling pathways regulating the pluripotency of stem cells, and the PI3K-Akt signaling pathway, all of which are reportedly associated with Prmt7 expression." (PMID 36013373, 2022). "Taken together, PRMT4, PRMT5, PRMT7 and potentially hnRNPA1 arginine methylation were required for the growth of multiple types of cancer cells." (PMID 33782401, 2021). "Given the complexity of the immune and antiviral responses, as well as links to B cell biology, it will be interesting to see if PRMT7 plays a role in autoimmunity and viral mimicry in cancer." (PMID 34440512, 2021). "This study is especially important in light of the complex regulation of GLI1 and GLI2 by PRMT1, PRMT5, and PRMT7 that controls cell senescence, self-renewal with potentially far-reaching implications in pluripotency and cancer-initiating cell biology." (PMID 34440512, 2021). "Further studies examining the effects of targeting PRMT7 in combination with chemotherapeutic drugs, specifically in breast and other cancer cell types, will help determine its full therapeutic value." (PMID 25605249, 2015). "In human tissues, only a single PRMT7 transcript was detected (~3.6 kb) and one protein, at 78kDa, was detected in two human cancer cell lines (HeLa and HuH7)." (PMID 25605249, 2015). "Conversely, blocking PRMT7 expression can lessen cancer cell migration and invasion." (PMID 41154773, 2025). "In NSCLC, PRMT7’s overexpression promotes cancer cell invasion by way of HSPA5 and EEF2 proteins." (PMID 40869229, 2025).
cancer (continued). "Overall, our findings suggested that the suppression of spermatogonial proliferation by apigenin treatment was mediated by the downregulated Prmt7/Akt3 pathway and the concentration should be taken into account in future applications of apigenin for cancer therapy in men." (PMID 34830091, 2021). "By summarizing the functions of PRMT7 in mouse embryonic stem cells (ESCs), induced pluripotent stem cells (iPSCs), muscle stem cells (MuSCs), and cancer stem cells, we found that PRMT7 was crucial for the pluripotency, proliferation, and differentiation of stem cells." (PMID 34712331, 2021). "Overall, our study supports that apigenin can interfere with mouse spermatogonial proliferation by way of the downregulated Prmt7/Akt3 pathway, which demonstrates that the concentration should be taken into account in future applications of apigenin for cancer therapy of men." (PMID 34830091, 2021). "Similar to PRMT7, PRMT4-, and PRMT5-regulated arginine methylation often co-occurred with phosphorylation and their methylation sites and sequences in the vicinity were vulnerable to cancer mutations." (PMID 33782401, 2021). "We then evaluated whether PRMT4, PRMT5 and PRMT7-regulated alternative splicing events are involved in cancer cell growth." (PMID 33782401, 2021). "Similarly, Prmt7 also played oncogenic roles in cancer cells by promoting cell proliferation and enhancing invasion." (PMID 34830091, 2021). "Furthermore, we also discuss the roles of PRMT7 in cancer, adipogenesis, male reproduction, cellular stress, and cellular senescence, as well as the future perspectives of PRMT7-related studies." (PMID 34712331, 2021). "Furthermore, in human cancer cells (HeLa) downregulation of PRMT7 expression conferred sensitivity to camptothecin treatment." (PMID 25605249, 2015). "In general, it has been suggested that PRMT7 may influence various cancers through its methylation." (PMID 40869229, 2025). "Additionally, PRMT7 has been shown to have a major regulatory function in a range of cancer cells." (PMID 41154773, 2025). "More importantly, PRMT7 inhibition potentiated doxorubicin-induced DNA damage and increased its cytotoxicity, indicating that this combined therapy might be a promising strategy for cancer treatment." (PMID 36293180, 2022). "Therefore, the PRMT7-mediated inhibition of cellular senescence may be a novel mechanism of tumorigenesis and cancer formation." (PMID 32859041, 2020). "In summary, our data demonstrated that specific inhibition of PRMT7 with SGC8158 blocks cell proliferation and DSB repair pathways, both HR and NHEJ, in human cancer cells, leading to cellular senescence." (PMID 36293180, 2022). "Collectively, our data suggest that SGC8158, a PRMT7 inhibitor, interferes with the DDR of cancer cells in combination with doxorubicin, leading to the potentiation of doxorubicin sensitivity." (PMID 36293180, 2022). "Taken together, our data demonstrate that PRMT7 is a critical modulator of cell growth and DDR, indicating that it is a promising target for cancer treatment." (PMID 36293180, 2022). "Recent reports revealed PRMT1, PRMT5, and PRMT7 regulate GLI1 and GLI2 activity in normal and cancer cells." (PMID 32859041, 2020). "PRMT7 was identified as an oncogene in breast, lung and renal cell carcinoma cancers and involved in the proliferation, invasion and metastasis of cancer cells by mediating the EMT or cancer-related signaling pathways 9-11." (PMID 37781082, 2023).
cancer (continued). "Since most of the chromatin regulators described here (LSD1, PRMT7, SETDB1, KDM5B, and ATF7IP) converge functionally, it will be crucial to identify additional cancer-specific factors the targeting of which may be less toxic." (PMID 36497341, 2022). "During EMT, PRMT7 methylates the scaffolding protein SH3 and multiple ankyrin repeat domain 2 (SHANK2) and activates endosomal focal adhesion kinase/cortactin signaling, contributing to cancer cell invasion, metastasis, and malignancy." (PMID 36293180, 2022). "Although the Cancer Dependency Map does not indicate that PRMT7 is essential for cell survival under normal growth conditions, it is possible that in specific contexts, PRMT7 plays a role in tumorigenesis." (PMID 34440512, 2021).